AMH (anti-Mullerian hormone)
Diseases named in the same sentence as AMH in open-access papers (continued):
Sharing a sentence is not in itself a finding about the gene and the disease.
Infertility (continued). "In our study, a high-normal TSH level had no adverse effect on clinical pregnancy rates, miscarriage rates, and live birth rates, regardless of adjustment for confounders such as age, AMH, quality of blastocyst, and causes of infertility." (PMID 32908501, 2020). "However, the effect of age on AMH appears to be consistent among various ethnicities/races and thus, age-specific AMH values provide clinical context particularly in the infertile woman." (PMID 33633682, 2020). "Although the present study investigated the association of AMH and FSH with serum levels of vitamin D in a sufficient sample of infertile women, this study could have several limitations." (PMID 32259002, 2020). "Several cross-sectional studies were conducted on populations of women with infertility, yielding largely negative results for an association between serum vitamin D and AMH concentrations." (PMID 32481491, 2020). "Besides the FSH and E2 assessment, AMH was measured in different groups as it is considered the most sensitive tool to determine the ovarian reserve before infertility develops and to predict the ovarian failure induced by cytotoxic therapy." (PMID 31531182, 2019). "However, in the women with tubal factor infertility AMH showed a fair prediction value for clinical pregnancy (AUC=0.64 [95% CI, 0.48-0.82]) along with the live birth (AUC=0.70 [95% CI, 0.55-0.85])." (PMID 30288481, 2018). "However, in the women with TF infertility AMH showed a fair prediction value for clinical pregnancy (AUC=0.64 [95% CI, 0.48-0.82]) along with living birth (AUC=0.70 [95% CI, 0.55-0.85])." (PMID 30288481, 2018). "In this study, we examined the AMH level and salivary alpha-amylase level in infertile women to analyze whether psychological stress influences the AMH level." (PMID 28693593, 2017). "Second, the strict selection of only white-Caucasian iNOA men might necessarily pave the way for setting novel cut-offs for AMH and AMH/tT in infertile men of different genetic backgrounds." (PMID 29247212, 2017). "Higher psychological stress was related to a decreased AMH level in infertile women and psychological stress may affect ovarian reserve." (PMID 28693593, 2017). "A total of 187 patients were prospectively involved in the analysis, using strict inclusion criteria, which allowed the study of a homogeneous, young, infertile patient population with a low BMI and a good ovarian reserve (mean female age 31.1 ± 4.1, AMH 3.1 ± 2.0 ng/mL and BMI 23.6 ± 3.0 kg/m2)." (PMID 28470453, 2017). "The kappa statistic of 0.76 was calculated between FSH level criterion and AMH level criterion as agreement on diagnosing occult premature ovarian insufficiency in women with oligomenorrhea and infertility while it was 0.93 between AFC and AMH for the same women." (PMID 29201666, 2017). "Therefore, the aim of this study was to identify the agreement between AFCs measured by transvaginal ultrasound (2D and 3D SonoAVC) and serum AMH levels in infertile women." (PMID 29246176, 2017). "Furthermore, AMH guided ovarian stimulation can lead to individualization of therapeutic strategies for infertility treatment." (PMID 26977116, 2016). "Serum AMH has also demonstrated its utility in the treatment of infertility." (PMID 26691645, 2015). "This is important in the clinical setting because women seeking treatment for infertility often have a low AMH; therefore, analysis with Elecsys Cobas will provide a better option for assessing AMH in this group of women in addition to its ability to measure levels as low as 0.5 pmol/l." (PMID 26394617, 2015). "AMH is a biomarker for canine SCT, and can therefore be of value in the diagnostic work-up of e.g. male dogs with signs of feminisation, hyperpigmentation, alopecia, subfertility, infertility and bone marrow suppression." (PMID 26209243, 2015). "Therefore, serum AMH has been recently applied to the assessment of ovarian reserve outside infertility treatment." (PMID 25510324, 2014).
Infertility (continued). "Since AMH is mainly produced in the growing ovarian follicles, it has been fully confirmed that serum AMH is positively related to the number of antral follicles, and the value of serum AMH has been widely used in predicting ovarian reverse for infertility treatment." (PMID 24932501, 2014). "Very low concentrations of AMH are associated with infertility in the case of pre-menopause and premature ovarian failure, and very high AMH concentrations with an absence of ovulation in women with polycystic ovarian syndrome." (PMID 22824005, 2012). "Although large AMH cohort studies describing falling AMH concentrations in adult women (mostly from populations attending infertility clinics) have recently been published, the data for AMH concentrations in children have until recently been considerably more limited." (PMID 21789206, 2011). "Like infertile populations, fertile women demonstrate declining AMH with advancing age." (PMID 21777422, 2011). "Furthermore, not only the AMH value but also the rate of AMH decline after surgery is of importance, as those that conceived spontaneously had a lower rate of AMH decline at 1 year postoperation compared to those that required infertility treatments." (PMID 40507534, 2025). "Furthermore, maternal age correlated positively with serum FSH level (r=0.229, p<0.001;***), with the duration of infertility (r= 0.143, p<0.001;***), and negatively with AMH level (r= - 0.249, p<0.001;***), and with the number of follicles (r= -0.263; p<0.001;***)." (PMID 38737557, 2024). "Here, we studied the possible influence of vitamin D on serum AMH in infertile men by conducting a secondary analysis of a randomized clinical trial testing the effect of high dose vitamin D + calcium versus placebo for 150 days on semen quality in infertile men with vitamin D insufficiency." (PMID 36855109, 2023). "Changes in AMH levels with age are seen before any other signs of the ovarian ageing process become notable, such as cycle length changes and infertility, which implies that AMH could specify a woman’s reproductive age more realistically than chronological age alone." (PMID 35705781, 2023). "Noting that higher AMH was associated with increased miscarriage rates within the PCOS related infertility patient population suggests that different levels of AMH may be representing different ongoing biomedical processes related to sustainable implantation within PCOS and non-PCOS patients." (PMID 37020210, 2023). "Recently, a case of 35 years old infertile women previously diagnosed as polycystic ovary syndrome (PCOS) showed multilocular cystic tumor with some solid portion that was diagnosed as adult type GCT with elevated AMH and hyperandrogenism that was diagnosed as having had been reported." (PMID 36922845, 2023). "In addition to its wide application in infertility care, such as determination of ovarian reserve, serum AMH levels may be useful in diagnosis of GCTs." (PMID 36922845, 2023). "Serum AMH has been reported to be lower in infertile men compared with fertile men but other studies have not been able to support this, which highlights that serum AMH preferentially may be used prognostically in infertile men rather than as a diagnostic marker of infertility." (PMID 36855109, 2023). "Therefore, finding out the biomarker such as preoperative AMH levels that could predict diminished ovarian reserve (DOR) after surgery is important to choose appropriate treatments to preserve fertility in infertile patients with ovarian endometriomas." (PMID 35582413, 2022). "Thus, in this study, we retrieved the data of infertile women who had been exposed to the GnRH agonist long-acting protocol or the antagonist protocol, and assessed their live birth rate by combining the basic characteristics: age, BMI and AMH levels." (PMID 35937797, 2022).
Infertility (continued). "The current study was undertaken to investigate the relationship between antimüllerian hormone (AMH) and polycystic ovarian syndrome (PCOS) phenotypes and to determine whether AMH is associated with pregnancy outcomes in infertile women undergoing their first in vitro fertilization (IVF) treatment." (PMID 35236324, 2022). "Fertile women may have higher AMH levels compared to infertile women." (PMID 36114550, 2022). "A study examining the distribution of serum AMH levels among infertile Asian women, including Chinese participants, found that age, ethnicity, obesity, and polycystic ovarian syndrome (PCOS) significantly impacted serum AMH levels." (PMID 40597965, 2025). "In this observational study with 50 patients with infertility receiving intracytoplasmic sperm injection (ICSI) treatment, women were classified according to ovarian responsiveness to anti‐Mullerian hormone (AMH) levels and the number of retrieved eggs." (PMID 41497357, 2025). "The improved biochemical measures of PCOS included androgen levels, lipids, HOMA-IR, blood glucose, insulin, LH/FSH ratio, DHEAS, SHBG, AFC, and AMH, while the improved symptoms of PCOS were irregular menstruation, infertility, OHSS, and weight gain." (PMID 40944281, 2025). "The analysis considered age, BMI, types of infertility, duration of infertility, basal FSH, AFC and AMH as confounding factors." (PMID 40055770, 2025). "More recently, AMH has been adopted in establishing a PCOS diagnosis, shown utility in the assessment of ovarian reserve in infertile patients, and assisted in guiding fertility care for women in this subgroup." (PMID 41196903, 2025). "In infertile PCOS women receiving letrozole for ovulation induction, increased levels of baseline LH/FSH ratio, AMH, and free androgen index were found to be negatively associated with response to letrozole treatment." (PMID 38807145, 2024). "The present study was aimed to derive nomograms for AMH and AFC among fertile and infertile women of Indian origin, indicating the trends in decline and the relationship between two ovarian reserve markers." (PMID 39446778, 2024). "Age cut off for decline in AMH and AFC in fertile women approximately 31 years using ROC analysis and Age cut off for decline in AMH and AFC in infertile women is approximately 34 years." (PMID 39446778, 2024). "Adjusting factors included age, AMH, AFC, infertility types, previous pregnancy history, number of embryos transferred, oocytes retrieved, available embryos and high-quality embryos." (PMID 39072274, 2024). "Eight statistically significant predictors were identified, namely age, duration of infertility, AFC, AMH, basal FSH, basal E2, FSH/LH ratio, and the duration of menstrual cycle." (PMID 39749019, 2024). "In all three groups, patients in the ICSI group were significantly older and had longer durations of infertility than those in the conventional IVF group, whereas body mass index (BMI), AMH, and bFSH levels were similar." (PMID 38228973, 2024). "Various studies have been published on nomograms based on AMH and AFC for fertile and infertile population." (PMID 39446778, 2024). "The correlation between AMH and various reproductive hormones such as estradiol, progesterone, testosterone, LH, and FSH in the context of infertility is an exciting topic in the field of reproductive medicine." (PMID 39336427, 2024). "Consistent with previous reports, marked distinctions were identified between the no‐PCOS and PCOS groups concerning variables such as age, BMI, AMH, AFC, infertile duration, FSH, LH, FSH/LH ratio, PRL, and T, as well as TG, TC, HDL, and LDL." (PMID 39139929, 2024). "The mean AMH and AFC values were higher in the fertile group compared to the infertile with the differences being significant in the age group of 20–25 and 25–30 years sub-groups." (PMID 39446778, 2024).
Infertility (continued). "Infertility in uterine problems may occur through various mechanisms, including cervical incompetence, abnormal uterine contractions, reduced blood flow to the ovaries, and decreased uterine and ovarian volume, which can negatively affect ovarian reserve factors and AMH levels." (PMID 37024902, 2023). "AFC, BMI, duration of infertility, LH level, ratio of LH to FSH, T level, AMH, triglyceride, Total cholesterol, LDL-C, HOMA-IR, number of oocytes retrieved, and number of MII oocytes were higher in the PCOS group than in the control group." (PMID 37537636, 2023). "In the infertile population, it was shown that TSH levels and age have an effect on AMH levels both in prematch and postmatch results." (PMID 37925426, 2023). "For IUI cycles where female partners had unexplained infertility, AMH values >2.1 ng/mL had double the CP rate compared to IUI cycles where women had AMH values <2.1 ng/mL." (PMID 38022255, 2023). "The baseline characteristics were comparable considering male age, female age, anti-Mullerian hormone (AMH), antral follicle counting (AFC), body mass index (BMI), type of infertility, and endometrial thickness among groups." (PMID 36896176, 2023). "Patients with high gonadotropin (Gn) and low estrogen levels but normal ovarian reserves, such as normal anti-Mullerian hormone (AMH) and inhibin B levels, often exhibit infertility." (PMID 36922772, 2023). "The parameters of age, duration of infertility, FSH, oocyte count, posttreatment AFC, BMI, LH, P4, and E2 were compared in each group based on the data of AMH level." (PMID 37122893, 2023). "The analysis involved adjusting for age, type of infertility, infertility duration, BMI, LH/FSH, AMH, and HOMA-IR." (PMID 37568475, 2023). "We found that combined low levels of serum AMH and high levels of serum FSH tend to be a better marker for semen quality compared to AMH alone, though only found in up to 16% of infertile men referred for andrological workup prior to ICSI." (PMID 36855109, 2023). "The predictive factors before the first cycle included maternal age, AMH, basal FSH, basal P, basal E2, infertility duration, and the number of left sinus follicles." (PMID 37370040, 2023). "Age, duration of infertility, type of infertility, FSH, LH, AMH, AFC, and BMI were included in the multivariate analysis eventually." (PMID 38047110, 2023). "Age, duration of infertility, BMI, FSH and FSH / LH were negatively correlated with AMH while the P was positively correlated in our study." (PMID 36539903, 2022). "The groups were similar for age, years of infertility, primary infertility rate, etiology of infertility, basal FSH, AMH, COS protocol, sperm concentration, and sperm motility." (PMID 34934401, 2022). "Age, BMI, infertility type, baseline FSH, LH, AMH and number of previous transferred cycles were comparable between groups; however, but infertility duration of patients in rsERT group was significantly longer." (PMID 36339409, 2022). "The variables in PSM model included female age, BMI, duration of infertility, type of infertility, basal sex hormone (E2, P, FSH, LH), AMH, insemination methods, the number of good quality embryos transferred and the type of embryos transferred." (PMID 36522703, 2022). "The mean patient age, etiology of infertility, baseline serum FSH, AMH and sperm concentration, and motility on oocyte retrieval day were similar between the groups after PSM." (PMID 34934401, 2022). "As expected, women in the moderate/severe OHSS group showed decreased age, BMI, body surface area, increased ovarian reservation markers (AMH, AFC, PCOS), and more primary infertility." (PMID 35872996, 2022). "We found four main predictive factors that should be taken into account when counseling infertility patients regarding IUI: female age, AMH, female infertility diagnosis and TPMSC." (PMID 36069921, 2022).
Infertility (continued). "There were no significant differencebetween the two groups in mean age, BMI, duration of infertility, type ofinfertility (primary or secondary), serum level of day 3 FSH, serum level ofAnti-Mullerian hormone (AMH), and sperm count of spouse." (PMID 35322951, 2022). "In this study, surgery and EST procedures were compared in terms of ovarian reserve (AMH) and ART outcomes, recurrence rate, and complications during the seven‐year follow‐up in endometriotic infertile women." (PMID 34262399, 2021). "In the women with discordant AMH and AFC (Group 2 and Group 3), age, FSH, duration of infertility, infertility diagnosis and etiology were comparable." (PMID 34454544, 2021). "In order to adjust potential confounders related to oocyte maturation, we conducted a binary logistic regression analysis including age, duration of infertility, BMI, basal FSH, AMH, antral follicle count, total doses of Gn, NT-4 level in FF." (PMID 34481496, 2021). "Analysis of the baseline characteristics of the four groups revealed statistically significant differences (p < 0.001) for age, BMI, AMH, AFC, FSH, infertility diagnosis and infertility etiology." (PMID 34454544, 2021). "Since there are limited studies that have examined this relationship, we performed a large cross-sectional study in infertile women to explore the correlation between serum DHEA-S and AMH levels." (PMID 33803980, 2021). "For women in Group 3 (low AFC and normal AMH levels), age, BMI, AFC, duration of infertility and infertility diagnosis were comparable in different COS protocols." (PMID 34454544, 2021). "A subgroup analysis of circDDX10 expression levels of the 210 human follicular GC samples divided by the quartiles (Q1, Q2, Q3, Q4) showed significant differences among the age, AMH, AFC, and infertility years (P < 0.01)." (PMID 33742605, 2021). "The significant variables identified following the selection procedure were recorded as follows: AFC, AMH, Age, E2, FSH, and infertility factors were incorporated in the COS pre-launch model." (PMID 33999860, 2021). "All possible important variables such as type and duration of infertility, AFC, serum AMH level, and MTHFR genotype were entered in the model." (PMID 34369004, 2021). "This study found that the expression level of circDDX10 in GCs derived from human follicular fluid has a positive correlation with serum AMH levels and AFC in infertile women." (PMID 33742605, 2021). "Premature ovarian failure (POF) usually manifests as amenorrhea and infertility; the serum follicle-stimulating hormone (FSH) level is increased, and the levels of anti-Müllerian hormone (AMH) and serum estrogen are reduced." (PMID 34526090, 2021). "Hence there may be an underestimation of infertility concerns and its association with FAI and AMH." (PMID 34108885, 2021). "Although many studies have been carried out on serum AMH levels and AFC, there is still some debate relating to differences in these variables between fertile and infertile women." (PMID 33907092, 2021). "Although the AMH level is highly correlated with the AFC, in clinical practice there is a discrepancy between the AMH level and the AFC in about 18–32% of women presenting at an infertility clinic." (PMID 34172798, 2021). "Mean age, body mass index (BMI), basal anti-Mullerian hormone (AMH), duration of infertility, and a number of retrieved oocytes were similar among the groups." (PMID 35058802, 2021). "Previous study also reported the expression of AMH and AMHR2 mRNA and protein in endometrial glandular epithelium and stromal cells in endometrial tissue obtained during infertility evaluation." (PMID 33263001, 2020). "As expected, women with DOR also had significantly lower serum AMH levels 0.4 ng/mL for DOR vs 2.5 ng/mL for tubal factor and 3.0 ng/mL for unexplained infertility, p < 0.001)." (PMID 32404103, 2020).